ZNF165 (zinc finger protein 165)
Description:
May be involved in transcriptional regulation.
Synonyms: CT53; ZSCAN7; LD65
Tractability: PROTAC: UniProt records ubiquitination sites on it; ubiquitination databases record sites on it.
Safety:
Unwanted effects reported when the protein is acted on. In parentheses: how it was acted on, where the effect was seen, and who reports it.
nausea and vomiting (source: ClinPGx)
Gene: Protein-coding gene on chromosome 6 (28,080,568 to 28,089,563, forward strand). Ensembl gene ENSG00000197279.
Subcellular location: Nucleus
Subcellular location (Human Protein Atlas): Microtubules; Nuclear speckles
Gene Ontology:
Molecular function: protein binding; DNA-binding transcription factor activity, RNA polymerase II-specific; RNA polymerase II cis-regulatory region sequence-specific DNA binding
Biological process: regulation of transcription by RNA polymerase II
Cellular component: nucleus; cytoplasm
Genetic constraint (gnomAD): Loss-of-function variants: 15 observed, 23.48 expected, observed/expected ratio (o/e) 0.64, 90% interval 0.43 to 0.98. The upper end of that interval is the gene's LOEUF score, 0.98, which puts it in group 4 of 6, group 1 being the genes least tolerant of losing a copy. Missense variants: 504 observed, 595.43 expected, observed/expected ratio (o/e) 0.85, 90% interval 0.79 to 0.91. Synonymous variants: 165 observed, 206.44 expected, observed/expected ratio (o/e) 0.8, 90% interval 0.7 to 0.91.
Homologues: Orthologues: chimpanzee ZNF165 (99% identical), macaque ZNF165 (96% identical), pig ZNF165 (83% identical). Paralogues in human: ZNF397 (44% identical), ZSCAN30 (44% identical), ZKSCAN8 (42% identical), ZKSCAN1 (41% identical), ZKSCAN3 (41% identical), ZKSCAN4 (41% identical), ZSCAN12 (40% identical), ZSCAN21 (40% identical), ZNF394 (39% identical), ZSCAN26 (38% identical), ZSCAN23 (37% identical), ZNF232 (36% identical), and 18 more.
Diseases named in the same sentence as ZNF165 in open-access papers:
ZNF165 is named in the same sentence as 22 diseases in open-access papers, as found by Europe PMC text mining. Sharing a sentence is not in itself a finding about the gene and the disease. The quoted sentences say what the papers report.
breast carcinoma (4 papers, 2015 to 2024). "Consistent with this, elevated ZNF165 expression in patients with breast cancer is associated with a greater metastatic potential (Hazard Ratio (HR) = 1.4; p=0.004)." (PMID 32515734, 2020). "Previously, it was reported that ZNF165 is a pro-oncogene and promotes the proliferation and migration of breast cancer cells by upregulating the TGF-β signaling pathway." (PMID 35692498, 2022). "Previous study suggests that ZNF165 is specifically expressed in the testis and tumor tissues and involved in the development of various malignant tumors, such as breast cancer, urinary bladder cancer, and hepatocellular carcinoma patients." (PMID 35692498, 2022). "Moreover, expression of ZNF165 was correlated with poorsurvival in breast cancer patients (HR=1.44;P=0.0260; Cox Regression)." (PMID 26567849, 2015). "Importantly, elevated ZNF165 mRNA expression correlates significantly with reduced survival time in breast cancer, indicating that expression of this protein may confer an aggressive tumorigenic phenotype." (PMID 32515734, 2020). "Notably, key transcription factors involved in ER+ breast cancer were highly enriched, including methylation-sensitive estrogen response elements (EREs) and ELF5 (ETS transcription factor family members), as well as architectural proteins CTCF and ZNF165." (PMID 38182927, 2024).
hepatocellular carcinoma (4 papers, 2004 to 2024). A malignant tumor that arises from hepatocytes. "We observed that overexpression of ZNF165 significantly increased the accumulation of kynurenine in the supernatant of liver carcinoma cells." (PMID 35692498, 2022). "We have found that ZNF165 mRNA is also expressed in the hepatocellular carcinoma, gastric cancer, colon cancer and non-small-cell lung carcinoma." (PMID 15354214, 2004). "RT–PCR, real-time PCR and Northern blotting analysis confirmed that ZNF165 mRNA was expressed in the hepatocellular carcinoma, gastric cancer, colon cancer and non-small-cell lung carcinoma." (PMID 15354214, 2004). "Humoral responses of hepatocellular carcinoma (HCC) patients against ZNF165 protein were determined by Western blotting using the recombinant ZNF165 protein." (PMID 15354214, 2004).
triple-negative breast carcinoma (4 papers, 2015 to 2024). An invasive breast carcinoma which is negative for expression of estrogen receptor (ER), progesterone receptor (PR), and human epidermal growth factor receptor 2 (HER2). "Here we report that ZNF165, a CT antigen frequently expressed in triple-negative breast cancer (TNBC), associates with SMAD3 to modulate transcription of transforming growth factor β (TGFβ)-dependent genes and thereby promote growth and survival of human TNBC cells." (PMID 32515734, 2020). "Using a large-scale, loss-of-function screening approach, our group previously identified the CT antigen, ZNF165, as essential for triple-negative breast cancer (TNBC) survival." (PMID 32515734, 2020). "We analysed ZNF165 in more detailbecause its depletion was also selectively lethal in theTGFβ-dependent, triple negative breast cancer (TNBC) cell line, WHIM12." (PMID 26567849, 2015).
urinary bladder cancer (3 papers, 2022 to 2023). A primary or metastatic malignant neoplasm involving the bladder. "Studies have also reported that ZNF165 is frequently expressed in human urinary bladder transitional cell carcinoma, which is confirmed as a novel diagnostic biomarker and a vaccine target in urinary bladder cancer." (PMID 37994325, 2023).
colon cancer (2 papers, 2004 to 2023). "Thus, colon cancer is associated with the TGFβ signaling pathway, which is activated by the ZNF165 gene." (PMID 37994325, 2023). "ZNF165 mRNA was expressed in six of 14 gastric cancer samples (43%), six of 14 colon cancer samples (43%) and in three of 14 non-small-cell lung cancer samples (21%)." (PMID 15354214, 2004).
non-small cell lung carcinoma (2 papers, 2004 to 2023). A group of at least three distinct histological types of lung cancer, including non-small cell squamous cell carcinoma, adenocarcinoma, and large cell carcinoma. "The mRNA expression of ZNF165 has been found in human HCC, gastric, colon and non-small-cell lung cancers." (PMID 15354214, 2004).
breast tumors (1 paper, 2020). "In support of this, our study of the testis protein ZNF165 has revealed a previously unrecognized mechanism by which TGFβ signaling is co-opted to promote malignancy in late-stage breast tumors." (PMID 32515734, 2020).
liver cancer (1 paper, 2022). An epithelial or non-epithelial malignant neoplasm that arises from the liver. "The high expression of ZNF165 impaired the survival of liver cancer patients and increased the death risk by 1.9-fold." (PMID 35692498, 2022). "More importantly, higher expression of ZNF165 was significantly found associated with lower overall survival and progression-free survival in liver cancer patients, suggesting that ZNF165 might play a role in liver cancer progression." (PMID 35692498, 2022). "In the present study, a higher expression of ZNF165 was observed in liver cancer tissues which was correlated with lower overall survival and progression-free survival." (PMID 35692498, 2022). "Consistently, the present study revealed the higher ZNF165 levels in liver cancer samples both in TCGA data and experimental results." (PMID 35692498, 2022). "Collectively, this study is aimed at investigating the specific effects and mechanism of ZNF165/AhR/CYP1A1 on liver cancer cell aggressiveness." (PMID 35692498, 2022). "In this study, we observed that ZNF165 was overexpressed in liver cancer tissues and the immune microenvironment; higher ZNF165 expression was correlated with lower overall survival in liver cancer patients." (PMID 35692498, 2022). "In this study, ZNF165 expression was investigated in liver cancer tissues and matched with adjacent normal samples through bioinformatics and experimental analyses." (PMID 35692498, 2022). "The data from TCGA data bank revealed that the mRNA expression of ZNF165 was significantly upregulated in liver cancer tissues as compared to paraneoplastic normal tissues." (PMID 35692498, 2022). "In order to evaluate whether ZNF165 is involved in the metabolism of kynurenine and tryptophan, we overexpressed ZNF165 in liver cancer cells." (PMID 35692498, 2022). "For investigating the mode of action of ZNF165 affecting liver cancer progression, factors and signaling pathways that might be modulated by ZNF165 were first analyzed." (PMID 35692498, 2022). "In order to investigate whether ZNF165 regulates the cell phenotypes by CYP1A1, we knocked down CYP1A1 and evaluated the proliferation and migration of the liver cancer cells." (PMID 35692498, 2022). "Furthermore, the downregulation of ZNF165 could significantly decrease the expression of AhR, CYP1A1, and CYP1B1 in liver cancer cells." (PMID 35692498, 2022).
lung carcinoma (1 paper, 2023). "The lung cancer risk SNP rs34662244 was located in the anchor of two enhancer–promoter interaction clusters with target genes ZNF165, ZSCAN16, and ZSCAN16-AS1." (PMID 36702236, 2023).
pancreas adenocarcinoma (1 paper, 2004). "In the SAGE database, one tag (AGGGAAAACC) representing ZNF165 was identified from the libraries of mammary gland carcinoma, prostate carcinoma and pancreas adenocarcinoma, respectively." (PMID 15354214, 2004).
tumor (8 papers, 2004 to 2025). "The study of CT antigen function generally, and ZNF165 in particular, has the capacity to reveal new principles underlying tumor cell regulatory networks." (PMID 32515734, 2020). "In this study, it was observed that the expression of ZNF165 was high in tumor tissues as compared to adjacent cancer tissues." (PMID 35692498, 2022). "Together these data demonstrate that despite differences in the genetic backgrounds of TNBC tumor cells, ZNF165 and SMAD3 exhibit significant co-occupancy on chromatin throughout the genome." (PMID 32515734, 2020). "Further studies to determine the nature of ZNF165-mediatedgene regulation in vivo will be necessary to better understand how ZNF165promotes tumour progression." (PMID 26567849, 2015). "In this report, we have examined ZNF165 mRNA expression in tumours of different histological types using various approaches." (PMID 15354214, 2004). "Sequencing results of RT–PCR products showed that the nucleotide sequence of ZNF165 expressed in tumours was also identical to that expressed in the testis." (PMID 15354214, 2004). "Analysis of the origins of publicly available expressed sequence tags as presented in Unigene and SAGE databases revealed that ZNF165 mRNA was expressed in tumours of different tissues." (PMID 15354214, 2004). "The nucleotide sequence of ZNF165 expressed in tumours is identical to that expressed in the testis." (PMID 15354214, 2004). "We observed a significant decrease in tumor size, suggesting that TRIM27 is essential for TNBC tumor growth in vivo and that inhibition of the ZNF165 transcriptional complex may be a promising avenue of therapeutic intervention." (PMID 32515734, 2020). "TRIM27 is essential for ZNF165 transcriptional activity and tumor growth in vivo." (PMID 32515734, 2020). "Our resultssuggest that ZNF165 may represent a mechanism to inhibit TGFβ signalling ina tumour cell-specific manner." (PMID 26567849, 2015). "ZNF165 mRNA detected in tumours is 2.2 kb, consistent with that found in the testis." (PMID 15354214, 2004). "Thus, ZNF165 mRNA was expressed in tumours of various histological types and normal testis." (PMID 15354214, 2004). "Therefore, there was no mutation in the ORF sequence of ZNF165 expressed in tumours (data not shown)." (PMID 15354214, 2004). "SCENIC predicted the top 4 transcription factors that differed expressed most between the two subgroups of tumour cells: SAP30, UQCRB, ZBTB33 and ZNF165." (PMID 40830065, 2025). "In summation, the molecules ZNF165, MXRA7, CEMIP, ARL4C, and CERCAM collectively represent prospective therapeutic nexus points in impeding tumor advancement." (PMID 39624211, 2024). "Although previous study suggested that ZNF165 is expressed in HCC tissues, the mechanism by which ZNF165 contributes to the tumor growth of HCC still needs to be elucidated." (PMID 35692498, 2022). "Although we found that ZNF165, as a new oncogene, promoted the development of HCC and was predicted to have tumor immunomodulatory function, the specific regulatory mechanism should still be further studied." (PMID 35692498, 2022). "We next perturbed TRIM27 as a means to inhibit the activity of the ZNF165 transcriptional complex and assess its impact on TNBC tumor growth and survival at the orthotopic site in mice." (PMID 32515734, 2020). "Taken together, these findings suggest that ZNF165 promotestumorigenesis by activating the TGFβ pathway, which in TNBC, isessential for tumour cell survival potentially in part through activation of theWISP1 oncogene." (PMID 26567849, 2015). "In addition, an endogenous interaction between ZNF165 and ZNF446 was detectable in TNBC tumor cell nuclear extracts, confirming these proteins interact in the relevant subcellular compartment." (PMID 32515734, 2020). "Importantly, we find that TRIM27 alone is necessary for ZNF165 transcriptional activity and is required for TNBC tumor growth in vivo using an orthotopic xenograft model in immunocompromised mice." (PMID 32515734, 2020).
tumor (continued). "The results of Northern blotting further confirmed that ZNF165 mRNA was expressed in tumours (data not shown)." (PMID 15354214, 2004). "However, a previous study has demonstrated that another member of the ZNF family, ZNF165 mRNA and its protein are expressed in HCC, indicating that ZNF family may be involved in tumor biology of HCC." (PMID 28637446, 2017). "Importantly, our study of ZNF165 reveals a criticalcontribution of an understudied oncogene, WISP1, to TNBC, highlighting howelaboration of CTA function can reveal cryptic aspects of the tumour cell regulatoryenvironment." (PMID 26567849, 2015). "Moreover, sera collected from HCC, whose resected tumour tissue samples did not express ZNF165 mRNA, were serologically negative to ZNF165 protein." (PMID 15354214, 2004). "Under real-time PCR, the ZNF165 mRNA was not only expressed in tumours and normal testis but also could be detected in paired noncancerous tissues and some normal tissues including the placenta, lung, liver, pancreas, spleen, thymus and colon." (PMID 15354214, 2004).
cancer (5 papers, 2004 to 2023). A tumor composed of atypical neoplastic, often pleomorphic cells that invade other tissues. "Also, its expression is predominant in most cancers, suggesting that ZNF165 may serve as a novel diagnostic biomarker and vaccine target in cancer as well as CD." (PMID 37994325, 2023). "It is reported that a series of cancers such as gastrointestinal cancer and urinary bladder transitional cell carcinoma expressed ZNF165." (PMID 35692498, 2022). "Consistent with the results of IHC, the western blot also revealed high expression of ZNF165 in the cancer tissues." (PMID 35692498, 2022). "ZNF165 is a functionally enigmatic cancer/testis (CT) antigen whose expression is usually restricted to germ cells but is aberrantly activated in tumors and is associated with the prognosis of a variety of tumors, mediated mainly by participating in the regulation of the TIME." (PMID 37324016, 2023).
infection (1 paper, 2012). The state of being infected such as from the introduction of a foreign agent such as serum, vaccine, antigenic substance or organism. "Genes in regions associated with control of infection included a zinc finger cluster (ZNF192, ZSCAN16, ZNF389, and ZNF165; P = 0.001), C19orf42/TMEM38A (P = 0.047), and DLGAP1 (P = 0.092)." (PMID 23082221, 2012).
ZNF165 also shares sentences with these, for which no sentence is quoted: gastric cancer (2 papers); urinary bladder transitional cell carcinoma (2); bladder cancer (1); endometrial cancer (1); glioma (1); hemochromatosis (1); lymphoma (1); prostate carcinoma (1); testicular germ cell tumor (1).